CXCL6 (C-X-C motif chemokine ligand 6)
Diseases named in the same sentence as CXCL6 in open-access papers (continued):
Sharing a sentence is not in itself a finding about the gene and the disease.
tumor (continued). "Additionally, CXCL6, together with other immune modulators such as CXCL8 and IL-8, contributes to the formation of an immunosuppressive microenvironment that facilitates tumor escape from immune surveillance, thereby promoting cancer progression and resistance to therapy." (PMID 39741907, 2024). "Neutralizing CXCL2 in the culture supernatant of DTX2‐overexpressing tumor cells and neutrophils partially restored IFNγ expression and proliferation of CD8+ T cells, while neutralizing CXCL6 did not." (PMID 39733452, 2025). "Chemokine levels were not related to histological tumor classification, but tumors with no expression of EGFR and p21 had significantly increased levels of CXCL8 and CXCL6, respectively." (PMID 29850390, 2018). "A wide range of diffusible mediators released from transformed or non-transformed cells in the tumor niche are known to induce EMT, including growth factors (EGF), cytokines (TGF-β, TNF-α), chemokines (CXCL8, CXCL6), and lipid mediators (leukotriene B4 (LTB4))." (PMID 34567000, 2021). "Interestingly, CXCL6 and other ARGs also showed negative correlations with checkpoints like VEGFB, KIR2DL1, LAG3, CTLA4, PDCD1, and IFNG, indicating they may promote immune surveillance and anti-tumor responses." (PMID 40943183, 2025).
cancer (73 papers, 2007 to 2026). A tumor composed of atypical neoplastic, often pleomorphic cells that invade other tissues. "Meanwhile, we also showed that higher expression levels of CXCL6 are associated with different types of human cancers and that CXCL6 protein levels are markedly higher in LUSC analyzed by using the UALCAN database." (PMID 41362669, 2026). "Dysregulation of CXCL6 function and expression has been strongly linked to a range of disorders, particularly cancers, fibrosis, and inflammatory diseases." (PMID 40539067, 2025). "CXCL6 is a chemokine involved in neutrophil trafficking and activation that has been implicated in the pathogenesis of several diseases and has been shown to promote cancer cell metastasis, fibrosis, and inflammation." (PMID 40070583, 2025). "Such as C-X-C motif chemokine ligand 6 (CXCL6) and TGF-β secreted by HCC cells were able to activate the extracellular signal-regulated kinase (ERK) 1/2 signaling pathway in cancer-associated fibroblasts (CAFs), which promoted the release of more CLCF1." (PMID 40109873, 2025). "Pan‐cancer analysis based on TCGA data revealed elevated CXCL6 expression across multiple malignancies, especially in CCA (P ≤ 0.01)." (PMID 40305734, 2025). "Studies have shown that CLCF1 produced by CAFs can stimulate TGF-β1 and CXCL6 secretion by cancer cells, thereby increasing the stemness of cancer cells and activating the ERK1/2 signaling pathway in CAFs." (PMID 38694506, 2024). "Cancer cells contact fibroblasts with tetraspanin 12 and transduce β-catenin signaling in CAFs, leading to the secretion of CXCL6, which promotes cancer invasion." (PMID 38730588, 2024). "The mutation frequencies of MCM4 and CXCL6 were 0.69% and 0.34% in GBM, which was too low to be identified by the methods based on cancer population." (PMID 37491836, 2023). "In their exploration of miRNAs in cancer development, they found that CXCL6 induced downregulation of the miRNA miR-515-5p." (PMID 36831112, 2023). "The upregulation of CXCL6 inhibited the cancer cell growth, survival, and metastasis by dysregulating miRNA‐101‐5p and miR‐515‐5p." (PMID 37491836, 2023). "In the personalized driver gene‐hallmark network, we found that the major contributions of MCM4 and CXCL6 were to different cancer hallmarks." (PMID 37491836, 2023). "CXCL3 is associated with the invasion and metastasis of various cancers and CXCL3 and CXCL6 are involved in the invasion and migration of various cancers." (PMID 35602512, 2022). "Mechanistically, CXCL6 in hypoxic cancer cells promoted the migration of TANs in vitro, and in turn promote NSCLC cells proliferation, migration and invasion." (PMID 34637697, 2021). "Autophagy is also recognized to contribute to oncogenic RAS driven cancer cell migration and invasion by inducing the secretion of the migration promoting CXCL6 chemokine and the transcription of pro-invasive molecules, including MMP2 and WNT5A." (PMID 34567000, 2021). "Some of these chemokines such as CXCL1, CXCL5, CXCL6 and CXCL8 are produced at high levels by tumors cells, whereas some are also produced by blood cells, cancer associated fibroblasts or endothelial cells." (PMID 32727083, 2020). "Overexpression of miR‐101‐5p was shown to suppress the aggressive phenotypes of cancer cells (in vitro) and pulmonary metastasis (in vivo) by regulating CXCL6." (PMID 31755218, 2020). "Cancer-related research showed that CXCL6 can promote the growth and metastasis of non-small-cell lung cancer (NSCLC) cells via down-regulated transcription of MiR-515-5p." (PMID 33489879, 2020). "Recent literature demonstrates the role of CXCR2 ligands in cancer and metastasis, such as CXCL6, one of the CXCR2 ligands that contributes to osteoclast differentiation and activation in a RANKL-dependent pathway." (PMID 30871004, 2019).
cancer (continued). "Despite the increasing number of studies indicating a role for CXCL1, CXCL5 and CXCL6 in different cancer types and processes, their relevance with view to the development of CRC is still rather limited." (PMID 18578857, 2008). "With the exception of CXCL6, all have been previously shown to be hypermethylated in other cancers or cancer cell lines." (PMID 17254359, 2007). "Among the DEPs involved in the IL17, Th17 cell differentiation and JAK-STAT signaling pathways, elevated levels of CSF3 and reduced CXCL6 were previously found in the serum of CRC patients, while our study also demonstrates their association with cancer-associated inflammation." (PMID 37228491, 2023). "CXCL6-mediated TANs infiltration contributes to hypoxic-related cancer progression." (PMID 34637697, 2021). "The apparent contrasting effect of autophagy on CXCL6 secretion reflects context dependent regulation of cytokine secretion by autophagy and highlights the need to explore more comprehensively the role of autophagy in mediator secretion in different cancer types and subtypes." (PMID 34567000, 2021). "CAFs-derived cardiotrophin-like cytokine factor 1 (CLCF1) stimulates HCC cancer cells to release TGF-β and C-X-C motif chemokine ligand 6 (CXCL6)." (PMID 36115852, 2022). "Accordingly, the cancer cells play a key role in neutrophil infiltration into TME by producing different signals including chemokines (e.g., IL-8, CCL2, CXCL6) and cytokines (e.g., IL-1β, IL-6, TNFα)." (PMID 36330498, 2022). "For other chemokines, CXCL11 was positively related to approximately all other chemokines except CCL14, CCL15, CCL16, CCL27, CCL28, CXCL6, and CXCL17 in almost all types of cancers." (PMID 35935945, 2022). "CTX also inhibits chemokines that bind to CXCR1 and CXCR2 receptors such as CXCL5, CXCL1/2/3, CXCL1a, CXCL6, and CXCL8 (IL-8) that are involved in cancer angiogenesis and metastasis." (PMID 34822613, 2021). "For example, chemokines, including CXCL6 and CXCL8, are one of the many secreted mediators that are upregulated in a Snail-dependent manner when EMT pathways are activated in cancer cells by EGF or TGF-β treatment." (PMID 34567000, 2021). "Of note, VAMP3 has been reported to be involved in CXCL6 and TNF-α release from the synovial sarcoma cell line SW982, indicating an active role of VAMP proteins in diffusible mediator secretion from cancer cells." (PMID 34567000, 2021). "There are reports shown that fibroblasts involve in the cross-talk of cancer cells and fibroblasts by secreting CCL2, CCL5, CXCL1, CXCL6, CXCL12, IL6, CXCL16 and others." (PMID 28465475, 2017). "In this way, our observation of the fast up-regulation of CXCL8, CXCL6 and CXCL1 by 1,25(OH)2D3 provides an additional aspect to the effects of the nuclear hormone on the immune response with impact on cancer immunology." (PMID 24250750, 2013). "The potential predictive roles of HER2, CXCL6 and BMP2 as biomarkers in the treatment of different cancers had suggested that they may have played significant roles in cancer biology." (PMID 39741907, 2024). "For example, in GBM individual TCGA‐06‐0648, the identified driver gene set contained both MCM4 and CXCL6, none of which were recorded as cancer genes." (PMID 37491836, 2023). "The cancer cell-derived EV were shown to modulate the dissemination pattern of metastatic cells and, in particular, MSC-EV have been seen to stimulate chondrocyte and synovial MSC migration via the CXCL5 and CXCL6/CXCR2 axes." (PMID 36076936, 2022). "Similarly, the overexpression of CXCL1, CXCL6, or CXCL12 has been shown to increase epithelial cell migration, proliferation, and growth, albeit in many cancer models." (PMID 35328555, 2022). "Interestingly, the same transcription factors are also emerging as key regulators for the expression of mediators such as cytokines (TNF-α), chemokines (CCL2, CXCL6, GRO, CXCL8, CXCL11), and growth factors (GM-CSF) in cancer cells." (PMID 34567000, 2021).
cancer (continued). "However, there were still many cancer promoting factors being increased, such as EGFR, G-CSF, CXCL6, etc.." (PMID 30805774, 2019). "Despite the increasing number of studies suggesting a cancer-related role for CXCL6, we observed no significant CXCL6 up-regulation in CRC tissues or CRLM, neither on the RNA nor on the protein level." (PMID 18578857, 2008). "But IL1RAP (p = 4.234 × 10−11), CXCL3 (p = 0), CXCL5 (p = 0), and CXCL6 (p = 0) gene expression levels had higher expression in ER-negative than ER-positive ones; whereas IL6ST was the only gene whose expression was higher in ER-positive cancer patients (p = 0)." (PMID 39201290, 2024). "In addition to their role in ECM construction, myCAFs may also enhance the stemness and proliferation of cancer cells by overexpressing secreted factors, including SEMA3C, POSTN, and CXCL6." (PMID 35986392, 2022). "In addition to these chemokine receptors, chemokine ligands such as CXCL1, CXCL2, CXCL5, CXCL6, CXCL8, and CXCL9 have been also significantly correlated with poor survival and metastasis in several cancers by recruiting MDSCs and suppressing the antitumoral activity of CD8+ T effectors cells." (PMID 32719800, 2020). "We studied therefore the expression of two relatively less well-studied chemokines CXCL6 and CXCL4 along with the better-studied CXCL8 (IL-8) and VEGF in both carcinoma and adjacent noncancerous tissue and correlated with several cancer indices, trophic factors, and patient survival." (PMID 29850390, 2018).
infection (37 papers, 2009 to 2025). The state of being infected such as from the introduction of a foreign agent such as serum, vaccine, antigenic substance or organism. "CXCL6, produced by endothelial cells and macrophages, promotes the attraction of neutrophils and monocytes to the site of infection, facilitating their entry into infected tissues and enhancing the inflammatory response." (PMID 38474048, 2024). "By day 14 post-infection, granzymes A and B were upregulated in Mamu-B*08+ RMs, as well as CXCL6 and CXCR6." (PMID 39502699, 2024). "IL-17A promotes CXCL5, which has a similar effect to CXCL6, and attracts neutrophils, eosinophils, and T cells to the site of infection, enhancing the local immune response." (PMID 38474048, 2024). "In humans, CXCL6 is secreted by macrophages and epithelial cells during inflammation to attract neutrophils to sites of infection." (PMID 38994364, 2024). "The combination treatment with both TMAO and CFT073 had significant additive effects on the release of CXCL11 and CCL20 and synergistic effects on the release of IL-8, CXCL1, and CXCL6 compared to CFT073 infection alone." (PMID 37111409, 2023). "We found that TMAO aggravated the release of several key cytokines (IL-1β and IL-6) and chemokines (IL-8, CXCL1 and CXCL6) from bladder epithelial cells during a CFT073 infection." (PMID 37111409, 2023). "Despite the differences in the magnitude of induction between each HBEC donor, combined, we observed a consistent trend of proinflammatory cytokine and chemokine (CCL2, CCL20, CXCL6, IL-6 and TNFα) inductions within 24 h post-infection with SARS-CoV-2." (PMID 34452468, 2021). "CXCL6 was upregulated in response to infection only at the 15 DPI time point, consistent with its role in chronic inflammation." (PMID 34805001, 2021). "CXCL6, which encodes a strong chemotactic protein mainly for neutrophils, was markedly downregulated in HCAEC after infection with S. agalactiae." (PMID 21437210, 2011). "Increased expression of IL-8 gene suggested that CXCL6 may function as a significant responsive factor during the process of pathogen infection." (PMID 34681113, 2021). "It has been suggested that CXCL6 could play a role in supporting chronic inflammation by facilitating neutrophil migration at a late stage of infection." (PMID 28018296, 2016). "CXCL6 and CXCL10 both belong to CXCL chemokine family, which primarily attract the neutrophils and T cells to sites of inflammation, infection, and trauma, respectively." (PMID 40224485, 2025). "Our data show that JCPyV-infected choroid plexus epithelial cells at 7 days post-infection, which represents two full viral life cycles, secrete a signature of proinflammatory chemokines, including CXCL8, CXCL5, CXCL6, and CCL2." (PMID 38874395, 2024). "These were accompanied by activation of genes related to cytokine production, including TGFB, CXCL6, TNFSF15 and XCL1, which prompt the recruitment of immune cells to the location of an ongoing infection." (PMID 36178892, 2022). "At 48 h post-infection, viral protein remained increased, and additional differentially expressed proteins were present, including MX1 and CXCL6." (PMID 32093375, 2020). "SpyCEP is a 170 kDa serine protease expressed on the surface of GAS, which proteolytically cleaves and abrogates the activities of the human chemokines CXCL1, CXCL2, CXCL6, and CXCL8/IL-8, impairing neutrophil recruitment to the site of infection." (PMID 29868516, 2018). "The list of genes with the greatest induction following Mtb:Δ-sigH infection at this time-point included CXCL1 (120-fold), PTGS2 (100-fold), CXCL6 (75-fold), CCL2 (53-fold), CXCL3 (40-fold), CXCL1 (43-fold) and CCL2 (38-fold) CCL5 (35-fold)." (PMID 22235255, 2012). "In this animal model of infection, COAM was shown to induce myeloid cell chemotaxis, in part through binding and activity of the chemokine granulocyte chemotactic protein-2/CXCL6." (PMID 23095573, 2012).
infection (continued). "Downregulation of CXCL6 after GBS stimulation was observed (2-fold after 4 hours and 12.9-fold after 8 hours of infection)." (PMID 21437210, 2011). "Namely, CD5, CD8A, CD6 and CD244, C-C and C-X-C motif chemokines (CXCL5 CXCL6, MCP-4, and CCL20), as well as CD40, PDL-1, CUB domain-containing protein 1 (CDCP1) and interleukin-12B (IL-12B) were elevated in the late infection group compared to the unexposed group." (PMID 41510260, 2025). "In summary, CXCL6, CXCL5, and CCL20 chemokines are important for the mechanism of immune signaling during infections, playing a fundamental role in recruiting immune cells to the site of infection and enhancing the local immune response." (PMID 38474048, 2024). "Additionally, we found that several cytokines and chemokines like IL-8, IL-1β, CXCL6, MCP-1 and MCP-4 were increased upon estradiol-stimulated CFT073 infection." (PMID 39362931, 2024).
bacterial infection (4 papers, 2019 to 2025). "There was evidence that indicated the up-regulation of CXCL6 gene expression in bovine mammary epithelial cell line with bacterial infection and in infected gland." (PMID 31921295, 2019).
gastrointestinal tumors (3 papers, 2008 to 2024). "CXCL6 was associated with angiogenesis in gastrointestinal tumors." (PMID 37491836, 2023).
inflammation (3 papers, 2017 to 2024). Aberrant reaction of the microcirculation characterized by movement of fluid and leukocytes from the blood into extravascular tissues. "In addition, CXCL6 is a chemokine with neutrophil chemotaxis, and it has been reported that CXCL6 expression is observed in acute lung inflammation caused by bleomycin administration and lung injury caused by nanomaterials." (PMID 39107780, 2024). "Therefore, we studied local mRNA levels of additional cytokines that have been associated with ILC3 homeostasis, such as CXCL6, IL-1β, IL-12, IL-18, and IL-23 and/ or intestinal inflammation, including IL-1β, TGF-β, IFN-γ, and TNF-α." (PMID 28505204, 2017).
respiratory disease (2 papers, 2019). "In Chinese Erhualian pigs, QTLs affecting respiratory disease were identified by a genome-wide association study; CXCL6, CXCL8, KIT, and CTBP2 were highlighted as candidates that might associated with resistance or susceptibility to swine enzootic pneumonia-like respiratory disease." (PMID 31656701, 2019).
benign tumors (1 paper, 2020). "A six-biomarker model including HE4, CA125, CEACAM1, CTSV, CXCL6, S100A4 and age was found to be the best model for discriminating between benign tumors and EOC with AUC 0.921 (0.863–0.979), sensitivity 0.897 / specificity 0.889 at best point cut-off (p = 0.025)." (PMID 33075095, 2020).
neurological disorders (1 paper, 2019). "Furthermore, all the cytokines/chemokines, with the exceptions of CXCL1, CXCL6, and IL-17A, were detected at higher levels in the patients with LNB, as compared to the patients with “other neurological and non-neurological disorders”." (PMID 31877982, 2019).
vasculopathy (1 paper, 2021). "Of note, the various CXC chemokines, such as CXCL4 (ELR-), CXCL5 (ELR+), CXCL6 (ELR+), CXCL12 (ELR−), CXCL13 (ELR−), and CXCL14 (ELR−), are thought to be associated with the development of SSc vasculopathy." (PMID 34774095, 2021).
CXCL6 also shares sentences with these, for which no sentence is quoted: inflammatory bowel disease (4 papers); osteosarcoma (3); Arthritis (2); idiopathic pulmonary fibrosis (2); influenza (2); kidney diseases (2); myeloma (2); osteoarthritis (2); steatosis (2); acute coronary syndrome (1); acute myeloid leukemia (1); acute respiratory distress syndrome (1); alcoholic hepatitis (1); amoebiasis (1); Anxiety (1); apical periodontitis (1); astrocytoma (1); bipolar disorder (1); bladder cancers (1); bordetella pertussis infection (1); carcinoma in situ (1); central nervous system disorder (1); chronic gastritis (1); chronic rhinosinusitis (1); Cirrhosis (1); Cognitive impairment (1); colorectal adenocarcinoma (1); cystic fibrosis (1); dengue (1); diabetic eye disease (1).
A further 35 diseases each share a sentence with CXCL6 in 1 paper.